IL10 (interleukin 10)
Diseases named in the same sentence as IL10 in open-access papers (continued):
Sharing a sentence is not in itself a finding about the gene and the disease.
pneumonia (continued). "First, patients with HIV and pneumonia exhibited elevated plasma levels of various cytokines, including IL-6, IL-8, IL-18, IL-1RA, IL-10, IP-10, MCP-1, and MIP-1β, compared to patients with HIV alone." (PMID 38251391, 2024). "Elevated levels of IL-10, IL-8, and IL-6 cytokines emerged as robust predictors of mortality in young adults with severe pneumonia due to SARS-CoV-2 infected." (PMID 38268832, 2024). "Lung tumor necrosis factor-α, interleukin (IL)-1β, IL-6, and IL-10 were significantly decreased at 48 hours after pneumonia induction in the exercise group compared with the control group." (PMID 38193770, 2024). "Patients with HIV and pneumonia presented elevated levels of cytokines and chemokines (IL-6, IL-8, IL-18, IL-1RA, IL-10, IP-10, MCP-1, and MIP-1β) compared to those with only HIV." (PMID 38251391, 2024). "In this patient, plasma IL-6 increased significantly at the outset of myocarditis, hepatitis, and pneumonia, while IL-10 increased exclusively at the onset of pneumonia, suggesting that both were associated with the development and regression of irAEs." (PMID 39139287, 2024). "The results showed that, compared with those in the control group, the proinflammatory factor levels in the serum and alveolar lavage fluid were significantly greater in the pneumonia group, while the anti-inflammatory factor IL-10 was significantly lower." (PMID 38903943, 2024). "With regard to cytokine release and systemic inflammation IL-1RA, tenascin-C, and sCD163 increased from baseline to the day of pneumonia diagnosis, IL-6, IL-10, procalcitonin and sRAGE decreased, and IL-8, MMP-8, and sTREM-1 remained unchanged in cases." (PMID 37415223, 2023). "Analysis of infected children during the 2009 influenza A (H1N1) virus pandemic revealed that levels of IFN-γ, IL-6, IL-8, IL-10, and other cytokines were higher in pneumonia patients than in non-pneumonia patients." (PMID 37249974, 2023). "This study showed a serial increase in HLA-DR expression and a decrease in IL-10 expression in BAL monocytes of survivors with pneumonia-related ARDS." (PMID 36552302, 2022). "When compared with the healthy children, children who were infected with HMPV pneumonia had a significantly lower level of IL-2 (p < 0.001) and higher levels of IL-4 (p < 0.001), IL-6 (p = 0.001), IL-10 (p < 0.001), and IFN-γ (p < 0.001)." (PMID 36496397, 2022). "Previous studies have also focused on the correlation between “IL-6 and IL-10 ratio” and disease severity, proving its unique clinical value in early diagnosis of severe pneumonia." (PMID 36544765, 2022). "Pretreatment with 1, 5-AF inhibited the protein and mRNA expression of iNOS in lung tissues, and upregulated the IL-10 level in serum of mice with acute pneumonia." (PMID 35782123, 2022). "• The overexpression of cytokines (i.e., TNF-α, IL-2, IL-10, IL-1, and IL-6) leads to development lung damage, cell death, severe pneumonia, ARDS, lung fibrosis, local or systemic thrombosis and multiple organ failure." (PMID 35422702, 2022). "In conclusion, serial increases in HLA-DR expression and decreases in IL-10 expression were observed in BAL monocytes of survivors of pneumonia-related ARDS." (PMID 36552302, 2022). "Compared with the HMPV pneumonia group and healthy control group, the former had a significantly lower level of IL-2 and higher levels of IL-4, IL-6, IL-10, and IFN-γ." (PMID 36496397, 2022). "A multiplex-biometric immunoassay showed that pneumonia cases had higher levels of serum cytokines (G-CSF, IL-2, IL-6, IL-10, IL-18, IP-10, MCP-3, and TNF-α) than bronchitis cases." (PMID 36119044, 2022). "Upon cytokine analysis, a higher level of IL-6, IL-8, and IL-10 was detected in severe pneumonia patients." (PMID 34305892, 2021).
pneumonia (continued). "In studies comparing postoperative serum cytokine levels in TTE and video-assisted thoracoscopic esophagectomy, patients undergoing the latter procedure had significantly lower postoperative IL-6, IL-8, and IL-10 level and postoperative pneumonia incidence." (PMID 33789620, 2021). "In patients with severe pneumonia, a very high level of cytokines (IL-6, IL-8, IL-10, and TNF-α) and large subtypes of macrophages have been observed but no activation of NK cells CD8+ T cells is evident." (PMID 34305892, 2021). "Generally, different populations of innate immune cells can release IL-10 in early infection including pneumonia, whereas T cells, enclosing Tregs, and NK cells seem to dominate at later stages." (PMID 33746948, 2021). "In both the IC and TX groups, IL-10 production was detected at low levels, with higher concentrations detected in IC patients with pneumonia." (PMID 34835067, 2021). "This study also comprised adoptive transfer assays to determine the impact of neutrophils able to produce IL-10 in a murine model of pneumonia." (PMID 33995357, 2021). "It should be noted that the Th1/Th2 ratio is higher in the control group than in the pneumonia group, but IL-10 also has a rising trend in the MPP group." (PMID 34803705, 2021). "The patients who developed pneumonia later on had already very high serum IL-10 levels on admission, and higher serum IL-10 levels predicted a poor clinical outcome at discharge from the hospital." (PMID 32106601, 2020). "In contrast, IL-10 protects hosts from pneumonia by C. kutscheri and S. pneumoniae infections by alleviating excessive lung inflammation." (PMID 32153580, 2020). "Both Serum IL-10 (p = 0.002) and IL-6 levels (p = 0.03) were also significantly higher in those who deceased or developed severe pneumonia, than in those with mild illness during early illness." (PMID 33199778, 2020). "Very interestingly, serum IL-10 levels were already very high on admission in SAH patients who developed later pneumonia compared to the patients who developed local infections." (PMID 32106601, 2020). "Firstly, our findings demonstrate the therapeutic potential of IL-10 overexpressing UC-MSCs in a clinically relevant model of live bacterial (E. coli)-induced pneumonia." (PMID 31200579, 2019). "In a rat model of pneumonia, IgM-enriched immunoglobulins enhanced the anti-inflammatory response by increasing blood IL-10 levels and reducing TNF-alpha in bronchoalveolar lavage fluid." (PMID 31797105, 2019). "Second, we provided insights into key effects of IL-10 overexpression on UC-MSCs in the setting of pneumonia-induced lung injury." (PMID 31200579, 2019). "The data indicated significant differences in the cytokine levels depending on the aetiology of pneumonia: decreased IL-6 for atypical bacteria, increased IL-10 for viral, increased IL-8 for Enterobacter spp., and increased TNF-α for L. pneumophila." (PMID 31183362, 2019). "These IL-10 overexpressing MSCs demonstrated a number of potentially important advantages over naïve UC-MSCs in our model of E. coli-induced pneumonia." (PMID 31200579, 2019). "IL-10 induces the apoptosis of mature DCs during chronic viral infections and decreases the number of live DCs during post-traumatic pneumonia." (PMID 30483258, 2018). "The levels of IL-6, TNF-α, and C-reactive protein were positively correlated with the serum levels of YKL-40, but the IL-10 levels were negatively correlated with YKL-40 levels in all 3 pneumonia subgroups." (PMID 30514252, 2018). "Proinflammatory cytokines such as IFN-γ, IL-4, IL-17A, and IL-10 play important roles in the immunization process against S. pneumonia." (PMID 29375585, 2017). "The decrease in the IL-6:IL-10 ratio to 3 in patients with severe pneumonia on D8 coincided with the temperature and respiratory frequency recovery to normal levels." (PMID 27905908, 2016).
pneumonia (continued). "The ROC curve of the IL-6:IL-10 serum levels ratio discriminated severe pneumonia cases at admission, and persistence of infection in the third day of antibiotic therapy, with positive predictive values of 93% and 89%, respectively." (PMID 27905908, 2016). "An anti-inflammatory activation in the lungs, through the expression of the anti-inflammatory IL-10, has already been reported by van der Poll and colleagues in a mouse model of S. pneumoniae pneumonia." (PMID 28702287, 2016). "The balance between IL-6 and IL-10 serum levels showed to be a more discriminative marker for severity definition and evaluation of recovery in patients with pneumonia." (PMID 27905908, 2016). "In the present study, IL-10 levels were higher in the group of patients with pneumonia than in patients with severe pneumonia in admission (1.99 x 3.68 pg/mL; P = 0.074)." (PMID 27905908, 2016). "In comparison with control mice, animals that received recombinant HMGB1 showed fivefold higher bacilli loads, the double of pneumonia and significant lower expression of IFNγ, TNFα and IL-17, while the expression of IL-10 was significantly higher." (PMID 26201072, 2015). "Persistently high levels of IL-6, IL-8 and IL-10 in BAL fluid or serum have been found in severe pneumonia and NCAP, reflecting an ongoing inflammation." (PMID 25849726, 2015). "Corroborating what we found in the localized intranasal pneumonia model, reduced IL-10 transcript production in Siglec-E KO mice was observed after low-dose GBS infection." (PMID 24391502, 2014). "The concentrations of the cytokines interleukin (IL)-1β, IL-6, keratinocyte-derived cytokine (KC) and IL-10 in lung homogenate were increased by pneumonia and, to a lesser extent, by MV." (PMID 24731244, 2014). "In pneumonia, MV led to a further dramatic increase of IL-1β, IL-6 and KC, while IL-10 levels remained unaffected." (PMID 24731244, 2014). "A relation between a detectable IL-10 and severe head injury has been shown, in accordance with pathophysiological links between brain injury, immunosuppression, and pneumonia development." (PMID 22431998, 2012). "The optimal cut-off concentrations that showed the highest prognostic accuracy (highest sensitivity and specificity) for IL-6, LBP and IL-10 in predicting a severe course of pneumonia were calculated using data from the ROC analyses." (PMID 22348735, 2012). "In the pneumonia group with subsequent septic shock, levels of IL-1β, IL-6, IL-8 and IL-10 were significantly increased before the onset of septic shock compared to patients without subsequent septic shock." (PMID 16280065, 2005). "• At the time of HAP diagnosis, TNF-α, IL-1β, IL-6, IL-8, IL-10 and E-selectin were significantly increased in pneumonia patients with subsequent septic shock compared to patients without subsequent septic shock." (PMID 16280065, 2005). "Likewise, a salivary PCT threshold >68.5 pg/ml and a serum IL-10 threshold >73.18 pg/ml each demonstrated 100% sensitivity and 100% specificity for pneumonia diagnosis, underscoring their exceptional performance." (PMID 41018059, 2025). "In our opinion, this is the first study to identify SNPs in antioxidant (SOD1, CAT, GPX1, NOS, HMOX1, and NQO1) and immunological (IL-1α, IL1B, IL6, TNF-α, IL10, LFA-1, CR2, IL17, IL13, DEFB123, SCART1, and ICAM1) genes as potential suspects for pneumonia resistance/susceptibility in Barki ewes." (PMID 40221769, 2025). "Besides, another study also explored the immune reactions in Chlamydia psittaci pneumonia and they found psittacosis cases with pneumonia had higher levels of serum cytokines (G-CSF, IL-2, IL-6, IL-10, IL-18, IP-10, MCP-3, and TNF-α) than bronchitis cases." (PMID 40236451, 2025). "In acute pneumonia, the activation of neutrophils, which act as first responders, results in the release of autocrine cytokines and chemokines such as IL-8, IL-4, IL-6, IL-10, IL-1β, transforming growth factor (TGF)-β, and TNF-α, among others." (PMID 38251391, 2024).
pneumonia (continued). "Elevated levels of IL‐6 and IL‐10 are indicative of the severity of inflammation and pneumonia." (PMID 37249293, 2023). "In line, the neutralization of IL-10 leads to better host survival in a murine KP-pneumonia model." (PMID 37637102, 2023). "Similarly, systemic IL-6 and Il-10 were upregulated at the diagnosis of pneumonia and showed downward trends throughout treatment, but without showing significant differences among study groups." (PMID 36788582, 2023). "Besides, the incidence of pneumonia was higher in the high baseline IL-10 group when compared with the low group (45.65% vs. 9.52%, p = 0.004)." (PMID 35222434, 2022). "A study indicated that elevation of IL-6 could be a biomarker for severity assessment or a prognostic indicator in patients with pneumonia, the similar tendency can be discovered in the balance between IL-6 and IL-10." (PMID 34725309, 2021). "Patients with higher KLF4 gene expression had a lower SOFA score as indicator for less severe pneumonia (mainly due to better oxygenation, higher mean arterial pressure, unaltered level of consciousness) and lower anti-inflammatory IL-10 serum levels upon hospital admission." (PMID 34589087, 2021). "Given the data available, it is possible that, in our model, neutrophils play a dual role in the lungs that, on the one side, protect the tissue from excessive immunopathology through the production of IL-10 but on the other side are required for bacterial clearance and pneumonia resolution." (PMID 33995357, 2021). "Serum IL-10 levels were already very high on admission in patients who developed later pneumonia." (PMID 32106601, 2020). "Measurement of inflammatory cytokine levels using ELISA showed that IL-1β, IL-6, TNF-α, IL-2, IL-8, IL-12, and IFN-γ levels were significantly enhanced, while IL-10 levels were significantly reduced in the lung homogenates of Spn-induced pneumonia mice, compared with the normal mice." (PMID 32460745, 2020). "IL-10 secretion is an essential component for the protective response against airway hyper reactivity and asthma and is involved in development of lung tolerogenic DCs after pneumonia." (PMID 30483258, 2018). "An important anti-inflammatory cytokine in pneumonia is IL-10." (PMID 27905908, 2016). "Nevertheless, given the results of the meta-analyses it is interesting to consider IL6 and IL10 genotype-dependent expression data in pneumonia or conditions which may precede or follow pneumonia." (PMID 27725770, 2016). "In the present study, the cytokines, TNF, IL-1β, IL-6, IL-8, IL-12p70, IFN-γ, IL-17A, IL-10 and IL-5, were detected in the serum of children with pneumonia and severe pneumonia at hospital admission, and IL-6 was the only cytokine associated with disease severity." (PMID 27905908, 2016). "The results show that the associations between the IL-10 gene -592C and IL-10 gene -1082A polymorphisms and pneumonia risk were not significantly altered." (PMID 25708204, 2015). "This meta-analysis suggests that there is no significantly increased risk of pneumonia associated with previously reported IL-6 and IL-10 polymorphisms." (PMID 25708204, 2015). "This IL-10 level increment dictates the resolution of inflammation and may be a positive prognostic indicator for recovery of pneumonia due to the combined therapy." (PMID 24565171, 2014). "Conversely, the level lung IL-10 were increased starting at 2 hours after initiation of AZM alone or in AMP plus AZM treated mice and sustained up to 6 hr post antibiotic treatment when compared to S. pneumonia infected untreated group (A: IL-6; B: IL-10; C: TNF-α and D: IFN-γ)." (PMID 24565171, 2014). "Pneumonia and MV each increased plasma IL-6, KC and IL-10 levels." (PMID 24731244, 2014). "In addition, IFN-γ was less frequently detected in the severe pH1N1 pneumonia group (P<0.001); but a relative increase in IL-10 was observed (P<0.05)." (PMID 22022504, 2011).
pneumonia (continued). "Thus, interplay and requirement of the HTL-derived IFN-γ and IL-10 in pneumococcal carriage and pneumonia will require further study." (PMID 20195541, 2010). "Using PCR-DNA sequence verdicts, the IL-1α (356-bp), IL-1β (423-bp), IL-6 (384-bp), TNFα (490-bp), IL-10 (306-bp), IFN-γ (321-bp), PRDX6 (434-bp), ATG7 (416-bp), NDUFS6 (405-bp), and NOX4 (396-bp) genes were found to have different SNPs in the amplified DNA bases linked to pneumonia." (PMID 40711280, 2025). "In our study, patients with HIV and pneumonia exhibit immune dysregulation, characterized by elevated levels of proinflammatory cytokines (IL-6, IL-8, IL-18), anti-inflammatory cytokines (IL-1RA, IL-10), and chemokines (IP10, MCP-1, MIP-1β) in their plasma, compared to the HIV group." (PMID 38251391, 2024). "IL-10 deficient mice are more susceptible to PA14-induced pneumonia but do not display bacteremia, suggesting that IL-10 helps to control local antimicrobial responses, but high lung levels may favor bacterial dissemination." (PMID 37426029, 2023). "Several iridoids were found to alleviate inflammatory response in A549 cells by reducing the release of proinflammatory cytokine IL-1β and IL-8, as well as increasing the expression of anti-inflammatory cytokine IL-10, which indicated that they may have therapeutic potential for pneumonia." (PMID 37764389, 2023). "Therefore, in addition to identifying IL-10 as a reliable predictor for the irAEs, we hope to find out if IL-10 could also play an eligible role in predicting pneumonia during ICI therapy." (PMID 35222434, 2022). "In addition, IL-10 are also abnormally elevated in pneumonia after esophageal cancer surgery." (PMID 34925324, 2021). "Moreover, IL-10 expression prior to bacterial infection was shown to inhibit neutrophil recruitment, resulting in insufficient bacterial clearance and increased mortality in a mouse model of pneumonia." (PMID 29881380, 2018). "According to the ROC curve analysis, at hospital admission, IL-6 serum levels equal or higher than 21.1 pg/mL and IL-6:IL-10 ratio of at least 9.61 may discriminate severe pneumonia from mild disease with a sensitivity of 76.5%, corresponding to a positive predictive value of 93%." (PMID 27905908, 2016). "Conversely, the expression levels of IL10, SOD1, CAT, GPX1, and NQO1 were significantly lower in the pneumonia group than in the healthy control group." (PMID 40221769, 2025). "This study aimed to evaluate the diagnostic and prognostic utility of salivary and serum interleukin (IL)-6, interleukin (IL)-10, and procalcitonin (PCT) in children diagnosed with pneumonia." (PMID 41018059, 2025). "Salivary biomarkers reflected these trends: salivary IL-10, IL-6, and PCT were all significantly higher in children with pneumonia than in healthy children (all p < 0.001)." (PMID 41018059, 2025). "Children with pneumonia exhibited significantly higher salivary concentrations of PCT, IL-6, and IL-10 compared to healthy controls, with strong correlations observed between salivary and serum levels." (PMID 41018059, 2025). "A reduction in IL-10 levels promotes an IFN-γ-dominated cytokine response, leading to mortality in animals with acute pneumonia." (PMID 40149081, 2025). "Our investigation used a PCR-DNA-sequencing procedure to illustrate the difference in immunological (IL-1α, IL1B, IL6, TNF-α, IL10, and IFN-γ) and antioxidant (PRDX6, ATG7, NDUFS6, and NOX4) genes in calves with pneumonia and healthy calves." (PMID 40711280, 2025). "During the initial phases of pneumonia, alveolar macrophages release inflammatory cytokines such as tumor necrosis factor-α (TNF-α), IL-10, and IL-6." (PMID 41018059, 2025). "In multivariate analysis, age <6 months (OR: 3.85), neutrophil-to-lymphocyte ratio (OR: 3.40), serum IL-10 (OR: 5.75), and salivary PCT (OR: 4.25) independently predicted severe pneumonia." (PMID 41018059, 2025).